AR (androgen receptor)
Diseases named in the same sentence as AR in open-access papers (continued):
Sharing a sentence is not in itself a finding about the gene and the disease.
prostate carcinoma (continued). "Interestingly, cellular senescence in prostate cancer (PCa) cells can be induced by either androgen receptor (AR) agonists at supraphysiological androgen level (SAL) used in bipolar androgen therapy or by AR antagonists." (PMID 32351687, 2020). "Following androgen stimulation in prostate cancer cells, AR is recruited to enhancer elements, along with DNA-PKcs, coregulator p300, and RNA Pol II suggesting that the interaction of AR and DNA-PKcs may be important for the regulation of specific transcriptional programming." (PMID 33062889, 2020). "Thus, the AR and its modulators are considered significant factors in the progression of prostate cancer and could be potential therapeutic targets." (PMID 33277473, 2020). "The contradiction might reflect the complexity of carcinogenesis, as exemplified by AR which generally drives proliferation of prostate cancer cells but also induces DNA double-strand breaks and cell cycle arrest in the presence of supraphysiological androgens." (PMID 33273988, 2020). "Indeed, FOXA1 has been hypothesized to be a mediator of hormonal response in breast and prostate cancer, and a hormonal regulatory complex involving FOXA1, GATA2 and AR has been shown to control gene expression in prostate cancer." (PMID 32850701, 2020). "High‐risk prostate cancer patients receiving primary ADT may develop rapid disease progression and benefit from early enrolment into clinical trials of novel androgen‐receptor targeted drugs, chemotherapy, radiopharmaceutical agent, immunotherapy or combination therapies." (PMID 33098372, 2020). "However, these clinical paradigm shifts with earlier application of second‐generation antiandrogens may result in earlier increased expression of AR‐Vs in prostate cancer patients." (PMID 32734688, 2020). "Hence, it is critical to identify new therapeutic targets that may alleviate accidental invasion promoting effects of inhibiting AR signaling in advanced state prostate cancer." (PMID 32820253, 2020). "Keeping in mind JNK’s roles in the apoptosis, proliferation, migration and DNA repair in prostate cancer, as well as the relationship between JNK and the androgen receptor, it might be hypothesized that GSTP1 polymorphic variants might have different impacts on PC development." (PMID 32183092, 2020). "Furthermore, our results imply that monocytic development may be affected by androgen levels and therapies that aim on reducing androgen signaling, such as AR antagonists used in prostate cancer treatment." (PMID 33193298, 2020). "Our study also provides a novel insight that targeting ERRα could be a potential androgen-deprivation strategy for the management of CRPC as pharmacological suppression of its activity could help to attenuate the intracellular production of DHT and AR signaling in prostate cancer cells." (PMID 32226548, 2020). "However, MYC is also reported to antagonize AR transcriptional activity in prostate cancer." (PMID 32630372, 2020). "Studies have shown that androgens can stimulate the expression of G1 cyclins and cyclin-dependent kinases (CDKs) and decrease the expression of CDK inhibitors; however, the mechanism by which AR stimulates the cell cycle progression in prostate cancer cells remains unclear." (PMID 33240734, 2020). "Notably, inhibition of ERRα activity by an inverse agonist XCT790 could reduce the DHT production and suppress AR signaling in prostate cancer cells." (PMID 32226548, 2020). "Collectively, our results provide insights into a new mechanism whereby AR-independent prostate cancer cell lines acquire heightened ability to proliferate and migrate and highlight hPCL3S targeting as a new potential interventional strategy against castration resistant prostate cancers." (PMID 32256978, 2020).
prostate carcinoma (continued). "Different theories suggest that castration-resistant prostate cancers have developed mechanisms that enable them to use steroids from the circulation more efficiently through de novo androgen synthesis, changed function of the androgen receptor, or even through estrogen receptor signaling pathways." (PMID 32594155, 2020). "Thus, it is conceivable that a combination of immune suppressive effects and the oncogenic role of androgen/AR axis could potentially augment the magnitude of SARS-CoV-2 infection in men with prostate cancer, resulting in an unfavorable cancer outcome." (PMID 32641750, 2020). "Therefore, we speculate that in prostate cancer cells MomC cytotoxicity correlates with AR activity." (PMID 32764580, 2020). "Therefore, patients with advanced-stage prostate cancer undergoing treatment with AR inhibitors may have a higher neoepitope load and hence benefit from immune checkpoint inhibitors." (PMID 32820253, 2020). "AR had been demonstrated to reduce cancer stemness by repression of CD44 and SOX2, on the contrary, loss of AR expression could upregulate STAT3 expression and lead to promote development of cancer stemness in prostate cancer cells." (PMID 32365531, 2020). "Targeting of the androgen receptor as a monotherapy or in combination with other conventional therapies has proven to be an effective clinical strategy for the treatment of patients with prostate cancer, and these therapeutic strategies are increasingly being investigated in breast cancer." (PMID 33062889, 2020). "However, in general, leveraging plasma specimens collected from different stages of prostate cancer may improve the characterization of key targets for prostate cancer, such as AR, in the real-time and genomic sub-classification of CRPC." (PMID 31689899, 2019). "Furthermore, AR has been shown to regulate EGFR expression in prostate cancer cells." (PMID 31151317, 2019). "Therefore, a hypothesis is currently proposed that naringenin acts through a series of genes (ESR1, PIK3CA, AKT1, MAPK1, and AR) to control prostate cancer cell proliferation." (PMID 30918758, 2019). "Thus, PLZF functions as tumor suppressor and interacts with AR in prostate cancer system, but it’s unclear whether similar links exist in germ line." (PMID 31142324, 2019). "Not only do these data demonstrate a collaborative effect of AR expression and deletion of p16INK4a in promoting prostate cancer initiation and progression, but also provide a new and biological relevant mouse model that mimics the age-dependent human prostate cancer phenotypes." (PMID 30677079, 2019). "Notably, NANOG was demonstrated to reprogramme prostate cancer cells by repressing the AR signalling axis and activating its own distinct transcriptional programme as well as engaging that of others such as MYC, leading to acquisition of a castration-resistant stem cell-like state." (PMID 30742096, 2019). "The androgen receptor (AR), a nuclear hormone receptor which, upon activation by androgens, translocates into the nucleus and binds to specific regulatory regions, plays a key role in the normal development of the prostate as well as in the pathogenesis of prostate cancer." (PMID 31689899, 2019). "Therefore, GR may maintain AR signaling in androgen-deprived environments by hijacking the transcriptional program of AR in prostate cancer cells." (PMID 31212954, 2019). "In addition, activation of the PI3K-Akt pathway in tumors with PTEN deletion has been shown to be associated with repressed androgen signalling in prostate cancer, while suppression of the PI3K-Akt pathway was demonstrated to activate androgen receptor signalling." (PMID 31151317, 2019). "Thus, possible correlation between AR expression and the signaling molecules involved in prostate cancer bone metastasis could be considered." (PMID 31137764, 2019).
prostate carcinoma (continued). "However, BMI1 exerts also some important oncogenic effects in prostate cancer cells through PRC1-independent mechanisms, involving direct binding to AR and consequent inhibition of MDM2-mediated AR degradation and sustained AR signaling in prostate cancer cells." (PMID 31366128, 2019). "Collectively, the mechanism of BAD inactivation by dysregulated PI3K/Akt signaling may be an important resistance mechanism in both PTEN‐deleted and PTEN–wild‐type prostate cancer and highlights a novel therapeutic strategy to increase apoptotic response to AR antagonists." (PMID 31228231, 2019). "These cell lines are representative of various stages of prostate cancer including (i) early-stage with androgen sensitivity (LNCaP) (ii) advanced-stage with the loss of androgen receptor (AR) function (PC3 and DU145) and (iii) castration resistant prostate cancer harboring repressed AR (22Rv1)." (PMID 31756185, 2019). "Strategies to inhibit AR functions may retard bone metastasis of prostate cancer." (PMID 31753020, 2019). "Indeed, the impact of USP17 on ELK-1 function may extend beyond its relationship with ERK, given the recent discovery of a physical and functional cooperation between ELK-1 and androgen receptor in advanced prostate cancer." (PMID 30854565, 2019). "Besides, GATA2 is a pioneer transcription factor for androgen receptor (AR) in prostate cancer, and increased GATA2 and its AR-independent transactivation of IGF2 could mediate taxane resistance through the activation of IGF1/insulin receptor signaling." (PMID 30935420, 2019). "In particular, breast and prostate cancer, share molecular similarities based on the idea that specific steroid receptors, the Oestrogen receptor α (ERα; referred to here as ER) for breast and Androgen receptor (AR) for prostate, have similar functions in driving both primary and recurrent disease." (PMID 30832393, 2019). "Studies on prostate cancers showed that binding of androgen to AR in the cytoplasm may initiate signal transduction pathways to regulate cellular proliferation and migration, known as non-genomic pathway, that requires neither AR nuclear translocation nor DNA binding." (PMID 31119584, 2019). "As above discussed, small cell neuroendocrine cancer is a very aggressive subset of prostate cancer that is rare at time of diagnosis but increasingly more frequent following emergence of resistance to AR-targeted therapies and thus represents one of the mechanisms of AR-resistance in CRPCs." (PMID 31366128, 2019). "Better therapeutic strategies may also be inferred from sequential single-cell characterization of CNV changes in CTCs over the course of treatment; MYC amplification occurred along with AR protein expression and AR amplification in a prostate cancer patient progressing through targeted therapy." (PMID 31635038, 2019). "Although some AR-mediated mechanisms by which ENZ influences sensitivity to radiation treatment are known, it remains unknown as to whether ENZ can radiosensitize in AR-independent (castration-resistant) prostate cancer and what factors may be involved in this process." (PMID 30933998, 2019). "In favor of the luminal origin is also the recent observation showing that androgen receptor mediates formation of the TMPRSS2-ERG fusion in human prostate cancer cells, thus suggesting that cancer initiating events may occur at the level of androgen receptor-positive luminal cells." (PMID 31366128, 2019). "In addition to its co-factor function, GATA2 might directly regulate androgen receptor mRNA and protein expression in prostate cancer cells." (PMID 31552182, 2019). "Such therapies are effective until the point at which prostate cancer, through a variety of mechanisms including but not limited to generation of ligand-independent androgen receptor splice variants, or intratumoral androgen production, overcome hormone deprivation." (PMID 31555580, 2019).
prostate carcinoma (continued). "In addition, miR-200a might inactivate BRD4-mediated AR signalling to inhibit the progression of prostate cancer." (PMID 31842887, 2019). "Genetic ablation of AR in prostate epithelial cells promotes the development of invasive prostate cancer, suggesting that therapeutic suppression of androgen/AR function induces unwanted signals that may promote the progression of surviving prostate cancer cells to an advanced metastatic stage." (PMID 30871130, 2019). "As prostate cancer is considered a heterogenous disease, for which only a few cell lines are available of which a subset is AR-driven, we next tested whether drug resistance as a result of TLE3 loss could be confirmed in two other prostate cancer cell lines; CWR-R1 and LAPC4." (PMID 31855178, 2019). "From our data, we deduct that the AR signaling pathway could be one of the mechanisms that lead to the therapeutic effect of kaempferol on prostate cancer cells and kaempferol may affect metastasis mediated by vasculogenic mimicry formation; in spite of these, further study remains necessary." (PMID 31871879, 2019). "Additionally, the splicing isoform ARv7 of the androgen receptor (AR) promotes enzalutamide-resistant in prostate cancer, which could be a potential target for anti-androgen therapy." (PMID 31065692, 2019). "Nevertheless, unlike squamous cell carcinoma, in which the inhibition of AR of CAFs could be beneficial, low levels or loss of AR in the stromal cells of prostate cancer are associated with poorer clinical outcomes." (PMID 30925918, 2019). "Finally, to investigate whether CNPY2 inhibited MYLIP-mediated AR degradation in prostate cancer cells, AR protein levels were examined by immunoblotting of lysates from either CNPY2 or MYLIP knockdown LNCaP cells." (PMID 29707137, 2018). "Moreover, the sensitivity difference of GSK-J4 treatment was also observed in correlation with other key pathways of prostate tumorigenesis in castration-resistant prostate cancer cell lines compared with AR-WT prostate cancer cells, suggesting a AR-dependent involvement of JMJD3." (PMID 29805743, 2018). "However, this proposed mechanism of action by AR activation cannot explain the expression of T:E fusion gene in advanced metastatic hormone therapy-resistant prostate cancer and AR-negative and androgen-independent prostate cancer cells." (PMID 30042415, 2018). "Another recent study suggests that AR variants are dependent on FOXA1 for sustaining a pro-proliferative gene signatures and agents targeting FOXA1 may represent novel therapeutic options for patients with castrate-resistant prostatic cancer." (PMID 29581876, 2018). "Finally, we showed that the loss of cells in direct co-cultures occurred with other prostate cancer cell lines and irrespective of AR expression in those cells." (PMID 29721186, 2018). "High AR levels in the epithelial cells were associated with higher Gleason score and higher serum PSA levels, but not with outcome, whilst, in contrast, low AR levels in the stroma were associated with more extensive disease, and a greater risk of prostate cancer-related death." (PMID 29721186, 2018). "The inability of these myofibroblasts to control the expansion of the cancer cells may explain why an AR-negative stroma is associated with more advanced prostate cancer." (PMID 29721186, 2018). "Results showed that LNCaP-TLX infectants exhibited no or negligible transactivation of ARE-luciferase reporter upon DHT treatment as compared to parental LNCaP cells, suggesting that overexpression of TLX could significantly suppress the AR transcription activity in prostate cancer cells." (PMID 29555975, 2018). "Additionally, they found that higher dosages of testosteronelead to more growth inhibition of relapsed tumors suggesting that the manipulation ofandrogen/AR signaling pathway may be a potential therapeutic target in AR-positivemetastatic prostate cancer." (PMID 29162647, 2018).
prostate carcinoma (continued). "AR is crucial for dampening TF expression, which could be important for increased TF expression and TF‐positive microvesicle release in androgen‐deprived prostate cancer patients." (PMID 29427323, 2018). "Interestingly, PKCδ expression in prostate cells is dependent on androgen signals, suggesting that therapeutic targeting of PKCδ might be highly dependent on the level of AR signaling in the prostate cancer." (PMID 30158439, 2018). "Our present findings show that TLX can directly target and repress the AR gene promoter, and also suppress the ligand-activated transcriptional activity of AR in prostate cancer cells, and through which it could enhance the NED progression and stemness of PCSCs in subpopulations of CRPC." (PMID 29555975, 2018). "Therefore, IKKα may be an attractive target for prostate cancer as the androgen receptor is the main driver of prostate cancer proliferation and inhibition of cell death." (PMID 30347849, 2018). "Indeed, in prostate cancer cells, AR has been shown to function as a co-activator of ELK1." (PMID 29518027, 2018). "To discover prostate cancer subgroups with distinct epigenetic and transcriptomic profiles, we selected the top most-variable genes based on RNA-seq and the most-variable regions among the high confidence peaks of AR, H3K27ac, H3K4me3, and H3K27me3 ChIP-seq data across the samples." (PMID 30464211, 2018). "18F–Fluorodehydrotestosterone (18F–FDHT) is a less widely used testosterone analogue binding the androgen receptor, whose activation is essential for the survival and proliferation of prostate cancer cells, and the central target of medical treatment of advanced and recurrent prostate cancer." (PMID 29782605, 2018). "Although this study focuses on the negative crosstalk, the positive crosstalk may provide the molecular mechanism by which hypoxia facilitates androgen/AR-signaling to drive prostate cancer development both in the primary site and in the metastatic bone environment." (PMID 30478344, 2018). "In the context of prostate cancer, tumor recurrence after androgen-deprivation therapy is due to the emergence of castration-resistant prostate cancer (CRPC), which is associated with increased AR activity that can be targeted by second-generation anti-androgen therapies." (PMID 29334357, 2018). "Notably, consistent with a role for AR loss in the emergence of neuroendocrine phenotypes, tumors in NPKA-CARN mice can display focal neuroendocrine differentiation, which has also been recently described in other mouse models of advanced prostate cancer." (PMID 29334357, 2018). "It is recently indicated tumor-initiating cells (T-IC), a small subset in cancer that has the capacities of self-renewal, mutipotent differentiation and tumorigenicity, may be affected by AR activation in prostate cancer, contributing to the progression of the malignant tumors." (PMID 29423076, 2018). "These puzzled observations also implicate that these fusion genes may bypass the AR regulation in advanced prostate cancer, and also these fusion genes-positive patients are susceptible to evolve into therapy-resistant and androgen-independent metastatic disease." (PMID 30042415, 2018). "Therefore, we investigated the in vitro and in vivo effects of SINE on the regulation of AR and ARv in prostate cancer and the molecular mechanisms underlying XPO1 regulated AR and ARv in order to design a novel therapeutic strategy for the treatment of prostate cancer and CRPC." (PMID 30450161, 2018). "Mechanistically, inhibition of the PI3K pathway increased AR signaling in PTEN‐deficient prostate cancer in part via relief of negative feedback to HER kinases; conversely, AR antagonism relieves feedback inhibition of AKT by reducing FKBP5‐mediated stability of the phosphatase PHLPP." (PMID 29572264, 2018).